RPL18AP3 (ribosomal protein L18a pseudogene 3)
Synonyms: bcm182; RPL18A_6_1273
Gene: Processed pseudogene on chromosome 12 (104,265,309 to 104,265,836, forward strand). Ensembl gene ENSG00000213442.
Diseases named in the same sentence as RPL18AP3 in open-access papers:
RPL18AP3 is named in the same sentence as 1 disease in open-access papers, as found by Europe PMC text mining. Sharing a sentence is not in itself a finding about the gene and the disease. The quoted sentences say what the papers report.
tumor (1 paper, 2020). "On the counterpart, 40435_at (SLC25A6), 33614_at (RPL18A, RPL18AP3), and 1657_at (PTPRR) are down-regulated (high expression values in normal class and low expression values in tumor class)." (PMID 33375940, 2020).